CTLA4 (cytotoxic T-lymphocyte associated protein 4)
Diseases named in the same sentence as CTLA4 in open-access papers (continued):
Sharing a sentence is not in itself a finding about the gene and the disease.
cancer (continued). "Recognition of the key role of immune responses against cancer has allowed the advent of immunotherapy, focused on the inhibition of negative immune checkpoints, such as CTLA-4." (PMID 32850353, 2020). "More interestingly, many inhibitory immune checkpoint genes, such as CTLA4, PD-1, and PD-L2, were upregulated in the SOH subgroup, suggesting that YAP1/TAZ may induce resistance of cancer cells to host immune response in GBM." (PMID 32717825, 2020). "Using this model, we were able not only to uncouple irAEs from the cancer immunotherapeutic effect (CITE), but also demonstrate that irAE can be avoided by preventing anti-CTLA-4 antibody-induced lysosomal degradation of the CTLA-4 molecules." (PMID 31991588, 2020). "The first study (phase 1b) evaluated the safety and efficacy of durvalumab (anti-PD-L1) and tremelimumab (anti-CTLA-4) combination in patients with advanced squamous or non-squamous NSCLC across five cancer centers in USA." (PMID 31196207, 2019). "Besides CTLA4 and PD1, LAG3 is now considered a major target for the mAb-based cancer immunotherapy." (PMID 31623599, 2019). "The cooperative anticancer effects of anti-CD137 with anti-CTLA4 or/and -PD-1 antibodies in several cancer types lead to promising directions in applying anti-CD137 antibody in the immune checkpoint therapies to advance cancer treatment." (PMID 31013788, 2019). "The success of CTLA-4 or PD-1/PD-L1 blockade catalyzed the enthusiasm for a new class of antibody that block negative immune checkpoint regulators for cancer therapy." (PMID 31690319, 2019). "Potential synergistic efficacy to boost immunity against cancer may also be implemented as already seen with GITR stimulation/PD-1 blockade and CTLA-4/ICOS stimulation." (PMID 31181772, 2019). "Additionally, CTLA-4 levels are inversely related to total CD4+ T cell population and directly related to HIV viral load and cancer progression." (PMID 31113482, 2019). "To date, there have been 6 immune checkpoint inhibitor antibodies (ipilimumab, nivolumab, pembrolizumab, avelumab, atezolizumab, and durvalumab) against CTLA4 or PD-1 approved by the U.S. Food and Drug Administration (FDA) for the treatment of a few cancer types." (PMID 31842801, 2019). "For instance, the expression of CD27, CTLA4, PDCD1LG2; TNFRSF18 were all significantly inhibited across different types of TCGA cancers as can be seen in the comprehensive study of more than 10,000 tumors comprising 33 diverse cancer types by utilizing data compiled by TCGA92." (PMID 31358815, 2019). "In addition, we noticed that the correlation between PD-1 and other immune checkpoints including LAG3, CTLA-4 and TIGIT is different for different types of cancer." (PMID 30607140, 2018). "Cancer cells can express ligands for T cell inhibitory receptors such as PDCD1 (PD-1) (ligand is CD274 [PD- L1]), CTLA-4 (ligands are CD80 and CD86), and HAVCR2 (aka TIM3) (ligand reported to be GAL9) to inhibit T cell activation and cytolytic T cell responses." (PMID 28822103, 2018). "These agents focus on receptors or ligands of effector cells as targets for cancer immunotherapy by inhibiting immune check points such as the programmed cell death protein 1 (PD-1, CD279) and its ligand (PD-L1) or the protein receptor CTLA4 (CD152)." (PMID 29747443, 2018). "The cancer immunotherapy has obtained an important progress by the use of therapeutic antibodies to CTLA-4, PD-1, and PD-L1 that antagonize immune checkpoints even though not all cancers respond to these antibody therapies." (PMID 29963061, 2018). "Cytotoxic T Lymphocyte Antigen 4 (CTLA-4 or CD152) exerts inhibitory activity on T cells, and since its oncogenic role in the progression of different types of tumors, it has emerged as a potential therapeutic target in cancer patients." (PMID 29682176, 2018).
cancer (continued). "Catherine Wu and her colleagues have identified a subcluster of MAGE-A cancer-germline antigens, located within a narrow 75 kb region of chromosome Xq28, that predicts resistance uniquely to blockade of CTLA4, but not PD-1." (PMID 30577797, 2018). "Besides PD-1, PD-L1 and CTLA-4, other checkpoint molecules (such as TIM-3 and LAG-3) have shown to inhibit the anti-cancer immune response." (PMID 30327656, 2018). "Considering the different affinity of CD86 and CD80 for CD28 and CTLA-4, respectively, and the constitutive expression of CTLA-4 in Treg cells, cancer cells could induce antigen tolerance towards themselves by modulating Treg cell functions." (PMID 30123257, 2018). "Other targets such as CD137 and OX40, unlike CTLA-4 and PD-1, work as immune activators and are as well under active investigation for cancer therapy." (PMID 30547012, 2018). "In this study, T cells of cancer patients, but not those of healthy donors, were activated by an anti-CTLA4 mAb produced by the virus." (PMID 29857493, 2018). "In addition, these strategies combined with other immune checkpoint therapy, such as CTLA-4 or PD1 blockage therapy, should yield more promising results for improved cancer immunotherapy." (PMID 29339767, 2018). "We then investigated whether the combination of lycorine hydrochloride and anti-mouse CTLA-4 would treat RCC and mRCC, one of the most common malignant tumors." (PMID 28416753, 2017). "Anti-CTLA-4 antibodies, RT, the combination of CTLA-4 antibodies and RT, or no treatment were administered to mice injected with 4T1 cancer cells in their flank." (PMID 28344743, 2017). "Antibodies against CTLA-4, progressive disease (PD)-1 (programmed death), and PD-1 ligands (PD1-L) represent a major step forward and are the first examples of broadly effective and durable cancer immunotherapies." (PMID 28348561, 2017). "Robust inflammation present in the HPV-active tumors, along with higher expression of immune checkpoint inhibitor targets TIGIT, CTLA4 and PDL-1, suggest that immune checkpoint inhibitor therapy may be a productive approach for these virally driven cancers." (PMID 28077784, 2017). "With the discovery of CTLA-4 as an effective immune checkpoint, blockade of CTLA-4 was found to promote antitumor immune reactions and gain notable clinical effectiveness as cancer therapy." (PMID 29299180, 2017). "The present study shows that the high levels of CTLA-4 and GARP, previously shown to be present on Tregs derived from human cancer ascites, may be directly induced by soluble factors within this ascites, and specifically IL-6." (PMID 29163543, 2017). "Perplexing is the fact that PD-1 and CTLA-4 checkpoint inhibitors, even when helped by cancer vaccines, are not effective against all cancer types, nor do they work in every patient with the same cancer." (PMID 28050779, 2017). "Immune-checkpoint blockade (i.e., blocking PD-1, PD-L1, or CTLA-4) has shown durable clinical effects in some (but not all) patients with various advanced cancers." (PMID 29112124, 2017). "The hypothesis is that hindering the “switch-off” receptors like CTLA-4 and PD1 in the lymphocytes, would set the immune system free to destroy cancer." (PMID 28348561, 2017). "Despite the success of the checkpoint blockade strategies targeting cytotoxic T lymphocyte antigen 4 (CTLA-4) and programmed death receptor 1 (PD-1), a large portion of cancer patients have not yet benefited from this novel therapy." (PMID 28300768, 2017). "At the same time, we also found that there were high expression of PD-1 and CD28, and low expression of CTLA-4 on T cells in cancer tissues and in distal nontumor tissues." (PMID 28061450, 2017). "Either CTLA4 inhibitor or PD-1 inhibitors did not give rise to high response rate in the treatment of patients with some cancer types." (PMID 29225597, 2017). "Therefore, the binding of tremelimumab to CTLA-4 efficiently competes with B7-1/2 binding to CTLA-4, thereby blocking the function of CTLA-4 in cancer." (PMID 27796306, 2016).
cancer (continued). "Some of the notable increases seen in cancer patients included subsets of T cells expressing basic leucine zipper transcription factor, ATF-like (BATF), PD-L1 and CTLA-4, which are inhibitory markers involved in immune checkpoint pathways and are increased upon T cell activation." (PMID 28936253, 2016). "These cancer-specific PTMLs strongly correlated with ATMLs from WES in both cancer types, and with clinical outcomes using three distinct immunotherapies (i.e., anti-CTLA-4, anti-PD-1, and ACT-TIL)." (PMID 27776519, 2016). "Comprehensive monitoring of the regulation of CPI and costimulatory molecules after administration of immunomodulatory antibodies (anti-PD1/PD-L1, anti-CTLA-4, anti-OX40, etc.)and cancer vaccines should help to guide the selection of the best combination and timing of this therapy." (PMID 27827885, 2016). "In cancer therapy, the beneficial results of combination immunotherapy targeting both costimulatory and co-inhibitory molecules (combined OX40/PD-1 or OX40/CTLA-4 mAb therapy) dramatically improved survival in the prostate, ovarian carcinoma, and sarcoma models." (PMID 28018344, 2016). "Our analysis does not support a similar use for cancer-gene panels in the prediction of response to CTLA-4." (PMID 26439694, 2015). "In the last two years, clinical trials with blocking antibodies to the negative checkpoint regulators CTLA-4 and PD-1 have rekindled the hope for cancer immunotherapy." (PMID 26347741, 2015). "To study this hypothesis, we used FACS analysis to quantify the expression of the three target receptors of CTLA4-FasL, namely CD80 (B7.1), CD86 (B7.2) and CD95 (Fas), on the different human cancer cell lines." (PMID 25227919, 2014). "Also studies in mice supported evidence that inhibitory molecules like CTLA-4 are involved in immune control and facilitated the use of anti-CTLA-4 antibodies in clinical practice to treat cancer." (PMID 25177323, 2014). "CTLA4-FasL was found to induce a significant, dose dependent killing effect in seven out of the ten cancer cell-lines we assessed, while it had almost no killing effect on the three non-malignant lines tested." (PMID 25227919, 2014). "In cancer patients, inflammatory changes indicate that IDO may be induced by soluble factors including IFNγ, TNF-α, IL-1β, soluble CD40 ligand (sCD40L) and CTLA-4 ligation to CD80/CD86 expressed by DC." (PMID 24147117, 2013). "Collectively, these data suggest that TIM-3 blockade may also be effective in re-awakening T cell responses in cancer patients, including those with AML, particularly in combination with anti-PD-1 or anti-CTLA-4 therapy." (PMID 24353898, 2013). "Cytotoxic T-lymphocyte antigen-4 (CTLA-4) is one such receptor, and its role as a key negative regulator of T-cell responses gives it the potential as a target for therapy in multiple cancer types." (PMID 23873089, 2013). "Thus, we inspected the gene expression levels of the examined genes (CD4, CD25, FOXP3, TGF-β, IFN-γ, IL-10, CTLA-4, PD-1, PD-L1, ARG1) in the CRC patients and confirmed they were all upregulated in the cancer patients." (PMID 22496728, 2012). "Notable examples include immune checkpoint inhibitors (e.g., anti-CTLA-4, anti-PD-1/PD-L1 antibodies), chimeric antigen receptor (CAR) T-cell therapy, and monoclonal antibody-based treatments, all of which have significantly improved patient outcomes in various cancers." (PMID 41228373, 2025). "Notably, in cancers such as COAD, BRCA, LUAD, READ, and CESC, tumors in the low-succinylation group exhibited elevated expression levels of PDCD1 (PD-1), CD274 (PD-L1), and CTLA4 at both the transcriptional and protein levels." (PMID 40463370, 2025). "The application of immune checkpoint modulators, such as anti-CTLA-4 and anti-PD-1 antibodies, along with adoptive immune cell therapies like CAR-T cells, has demonstrated unexpected anti-tumor effects across a spectrum of cancers, ushering in a new era for cancer treatment." (PMID 39980564, 2025).
cancer (continued). "Interestingly, multiple genes encoding cell surface immune checkpoint receptors and their ligands were transcriptionally regulated by IRF4, including PD-L1 (CD274), PD1 (CD279), CTLA4 (CD152), B7-2 (CD86), LAG3 (CD223), and PD-L2 (CD273), in these virus-infected cancer cells." (PMID 40733503, 2025). "Inhibitory receptors such as CTLA-4, PD-1, LAG3, and PD-L1, which regulate immune responses, alongside cytokine receptors like il2-R, il10-R, and TGFbRII, which control the proliferation and differentiation of immune cells, have become important therapeutic targets for cancer immunotherapy." (PMID 40011465, 2025). "ICIs were grouped by mechanistic class (PD-1, PD-L1, CTLA-4, LAG-3), and additional variables included polypharmacy (number of unique drugs), sex, age, and cancer diagnosis (assigned using both indication keywords and manual curation of cancer-specific medications)." (PMID 40630567, 2025). "Other work has identified FMRP as a potential target for cancer immunotherapy, as it regulates immune cell metabolism, suggesting that inhibition of FMRP could overcome resistance to anti–PD-1, anti–PD-L1, and anti–CTLA-4 therapies." (PMID 41184982, 2025). "Additionally, the upregulation of cell-mediated immune-related molecules such as CTLA4 and PFR1 suggests that CMC-AL may enhance the body’s immune response to cancer cells." (PMID 40359186, 2025). "Notably, abatacept (a CTLA-4-Ig fusion protein that binds CD80/CD86) has demonstrated the ability to modulate T-cell activation and has shown antitumor activity in immunologically active cancers." (PMID 40445003, 2025). "This study investigates a cohort of patients treated with an anti-CTLA-4 ICI, ipilimumab, and characterizes the irAEs, evaluates irAE incidence as a predictor for improved cancer outcome, and examines whether a low NLR predicts irAE occurrence and cancer outcome." (PMID 40563660, 2025). "Since the first checkpoint inhibitor, ipilimumab, which targets CTLA-4, gained FDA approval, immunotherapy, especially anti-PD-1 and anti-PD-L1 antibody therapies, has shown inspiring clinical activity in various types of cancers and has become the new standard of anti-cancer therapy." (PMID 40591071, 2025). "Besides, the Immunoscore (IPS) dataset retrieved from The Cancer Immunome Atlas (TCIA) was used to ascertain if the expression level of RGS1 influences the efficacy of antibody responses against anti-PD-1 and CTLA-4 for a further examination of the connection between RGS1 and immunotherapy reaction." (PMID 37735297, 2024). "Therefore, might utilizing three ICIs specifically targeting PD-1/PD-L1, CTLA-4, and LAG-3 provide a better alternative for cancer patients?" (PMID 38390331, 2024). "On the contrary, the transmembrane proteins that we will focus on, namely PD-1, CTLA-4, LAG-3, TIM-3, and TIGIT, are involved in the downregulation of a T-cellular immune response, including an anti-cancer immune response, preventing the cytotoxic T cells from killing cancer cells." (PMID 38893211, 2024). "However, cancer cells release transforming growth factor beta (TGF-β), which can increase the expression of CTLA-4, leading to T-cell exhaustion; in the exhausted state, T-cells exhibit decreased functionality and can potentially exert immunosuppressive effects." (PMID 38474377, 2024). "When we believe that immunotherapy could be a panacea in cancer care, we combine anti-PD1/L1 with another CPI (such as anti-CTLA-4, anti-IDO1, anti-TIGIT) and with agents that target immune factors (e.g., IL-2) and effectors (e.g., dendritic cells, T cells, macrophages, NK cells), etc." (PMID 38539487, 2024). "Suppose PDL1 (like LAG3) is not only a CPI but also a stemness marker (unlike other CPI), could that explain why anti-PD1/L1 (and anti-LAG3) is a better anti-cancer treatment compared with those other CPI (e.g., anti-CTLA4, anti-IDO1, anti-TIGIT), which are bona fide immunotherapy?" (PMID 38539487, 2024).
cancer (continued). "The significant utilization of glucose by cancer cells as an energy source leads to the accumulation of extracellular lactate in the TME that weakens CD8+ T-cell cytotoxicity, decreasing IFN-γ production while fostering T-cell apoptosis through increased expression of CTLA-4 and PD-L1." (PMID 38891056, 2024). "However, compared to other cancer types such as melanoma, the response to CTLA-4 inhibitors alone in NSCLC patients is not as prominent." (PMID 39308869, 2024). "Notably, the occurrence of bullous pemphigoid was observed in cancer patients treated sequentially with PD-1 and CTLA-4, but not in those treated with ipilimumab monotherapy." (PMID 39795946, 2024). "Starting in 2011, with the approval of anti-CTLA-4 treatment by the U.S. Food and Drug Administration (FDA) for advanced stage melanoma, several ICIs have been approved for cancer immunotherapy and proven effective in boosting the activation of immune responses against cancer cells." (PMID 38611048, 2024). "While immune checkpoint blockade (ICB) agents, such as those targeting PD-L1 or CTLA4 pathways, have demonstrated clinical efficacy in some cancers, current ICB treatments do not have activity in all cancers, sometimes due to an unfavorable tumor immune microenvironment." (PMID 38358346, 2024). "Notably, the development of the first CTLA-4 blocking antibody in 1996 and the subsequent FDA approval of ipilimumab in 2011 marked a significant breakthrough, showing remarkable success in treating melanoma and other types of cancer." (PMID 38743676, 2024). "In the realm of cancer treatment, immunotherapy has recently come to the forefront as a promising area, with Immune Checkpoint Inhibitors (ICIs) such as anti-PD1, anti-programmed death ligand-1 (PD-L1), and anti-cytotoxic T-lymphocyte antigen-4 (CTLA-4) in treating ccRCC." (PMID 38970774, 2024). "In 1996, Allison and colleagues showed that antibodies blocking CTLA-4 could induce tumor rejection in mice, suggesting the potential to treat cancer by modulating the immune system rather than directly targeting cancer cells." (PMID 39584990, 2024). "Programmed cell death-1 (PD-1)/programmed cell death ligand-1 (PD-L1) pathway, cytotoxic T-lymphocyte antigen-4 (CTLA-4) pathway, and the recently discovered lymphocyte-activation gene 3 (LAG-3) pathway, play a critical role in boosting the body’s natural immune response against cancer cells." (PMID 38482205, 2024). "Therefore, LAG3 serves as the third clinical checkpoint in case of limited or even no response in 60 to 80% of cancer patients in PD1/CTLA-4 axis immunotherapy." (PMID 38291496, 2024). "As TIM-3 has a negative impact on immune regulation, the blockade of TIM-3 inhibition using an antibody may induce an antitumor immune response against some cancers, such as colorectal cancer, in which anti-CTLA-4 and anti-PD-1 antibodies were not effective." (PMID 38255322, 2024). "Since the CTLA-4 pathway functions in secondary lymphoid organs while the PD-L1 pathway works within the TME, targeting CTLA-4 and PD-L1 simultaneously using bsAbs may enhance the antitumor benefit for cancer immunotherapy." (PMID 38257366, 2024). "Therefore, in murine cancer models, anti-CTLA4 and EZH2 inhibition could cooperate to provide strong anti-cancer immune responses." (PMID 39227959, 2024). "Additionally, In the cancer patients treated with anti-PDCD1 (Pembrolizumab), anti-CD274 (Atezolizumab), or anti-CTLA4 (Ipilimumab) of the K-M plotter database, elevated KLRB1 expression exhibited better OS and progression-free survival (PFS) after grouping with KLRB1 expression median value." (PMID 37988189, 2023). "Remarkable clinical outcomes have been achieved in cancer immunotherapy of several types of cancers based on ICB antibodies, especially those blockading the programmed cell death protein 1/programmed death-ligand 1 (PD-1/PD-L1) or cytotoxic T lymphocyte antigen 4 (CTLA-4) pathway." (PMID 37265604, 2023).